TGFB3 (transforming growth factor beta 3)
Diseases named in the same sentence as TGFB3 in open-access papers (continued):
Sharing a sentence is not in itself a finding about the gene and the disease.
Loeys-Dietz syndrome (7 papers, 2018 to 2024). Loeys-Dietz syndrome is a rare genetic connective tissue disorder characterized by a broad spectrum of craniofacial, vascular and skeletal manifestations with four genetic subtypes described forming a clinical continuum. "Among the genes queried, COL3A1 and aggregated testing of Loeys-Dietz syndrome-associated genes (TGFBR1, TGFBR2, SMAD2, SMAD3, TGFB2, TGFB3) were the leading signals of enrichment, consistent with prior studies [21•, 24, 25]." (PMID 37979122, 2023). "These include syndromic diseases associated with aortic aneurysms, including Marfan’s and Loeys Dietz Syndromes (LDS), due to mutations in TGFβ signaling genes FBN1, TGFBR1, TGFBR2, TGFB2, and TGFB3." (PMID 30307970, 2018). "Among these, Loeys-Dietz syndrome (MIM # 609,192) shows mutations in other genes which are involved in the same pathway of FBN1 and include TGFBR1 (MIM * 190,181), TGFBR2 (MIM * 190,182), SMAD3 (MIM * 603,109), TGFB2 (MIM * 190,220), TGFB3 (MIM * 190,230) and SMAD2 (MIM * 601,366)." (PMID 39008115, 2024). "Finally, we did not consider genes encoding TGF-beta ligands TGFB2 and TGFB3, or SMAD2, although these were described recently to contribute to Loeys-Dietz syndrome." (PMID 31795342, 2019).
myocardial infarction (7 papers, 2017 to 2024). Gross necrosis of the myocardium, as a result of interruption of the blood supply to the area, as in coronary thrombosis. "Although an elevated and prolonged induction Tgfb3 mRNA has been reported in experimental models of myocardial infarction and a polymorphism of TGF‐β3 is associated with changes in LV geometry in hypertensive patients, very little is known about its function in cardiac remodeling." (PMID 38872461, 2024). "During disease progression, such as myocardial infarction, the expression of Tgfb3 will increase and act as a negative regulator of fibrosis." (PMID 35964009, 2022). "In this study we found that the expression level of TGFβ3 was higher in human myocardial infarction (MI) tissues than in normal tissues, and interestingly, it increased with the development of fibrosis post‐myocardial infarction (post‐MI)." (PMID 30983140, 2019). "CILP1 expression was determined in mouse LV infarct tissue (MI) and remote non-infarcted area (RA) at 5 days and 4 weeks following myocardial infarction and compared to connective tissue growth factor (CTGF), collagen type I (COL1A1), TGFβ1 and TGFβ3." (PMID 29167509, 2017).
aortic aneurysm (6 papers, 2015 to 2025). A ruptured aneurysm located in the wall of the proximal portion of the descending aorta proceeding from the arch of the aorta. "The phenotype of the families was consistent with other LDS types and more specifically with other (likely) pathogenic TGFB3 variants that included aortic aneurysm, bifid uvula, arachnodactyly, scoliosis, and palate deformities (PP4)." (PMID 37719708, 2023). "These suggestions are consistent with the clinical findings indicating the presence of aortic and mitral valve diseases and aortic aneurysm in the LDS patients with genetic mutations in TGFB2 (LDS4) or TGFB3 (LDS5)." (PMID 32456345, 2020). "Here, we report on 43 patients from 11 families with syndromic presentations of aortic aneurysms caused by TGFB3 mutations." (PMID 25835445, 2015). "Here, we report that TGFB3 mutations cause a syndromic form of aortic aneurysms and dissections, characterized by cardiovascular, craniofacial, cutaneous, and skeletal anomalies that significantly overlap with other TGF-β vasculopathies, particularly those within the LDS clinical spectrum." (PMID 25835445, 2015). "TGFB3 is a tier 1 gene from the PanelApp aortopathy and CTD gene panel and is associated with autosomal dominant Loeys–Dietz syndrome 5 and aortic aneurysm." (PMID 40194966, 2025).
autoimmune disease (6 papers, 2016 to 2022). A disorder resulting from loss of function or tissue destruction of an organ or multiple organs, arising from humoral or cellular immune responses of the individual to their own tissue constituents. "Many reports have suggested that TGFβ3 has potential applications in wound healing, cartilage repair, and autoimmune diseases by modulating cellular proliferation and migration." (PMID 35964077, 2022). "Several recent lines of evidence suggest a role for TGFβ-3 in the pathogenesis of autoimmune diseases." (PMID 35328606, 2022).
Infertility (6 papers, 2015 to 2025). "Knock out (Tgfb1tm1(Tgfb3)Kul/Tgfb1tm1(Tgfb3)Kul) in mice causes infertility (J:204892 from MGIdatabase)." (PMID 40422207, 2025). "As for TGFB3 rs3917158, only in the case of heterozygous subjects, an association with infertility was significant [OR = 1.37 (95% CI 1.01–1.87), p = 0.041]." (PMID 26612435, 2015). "In the case of TGFB3 rs3917158 a significant association with infertility in heterozygous subjects was found, with odd ratio of 1.37." (PMID 26612435, 2015). "Heterozygosity in TGFB3 rs3917158 was also associated with the infertility [OR = 1.37 (95% CI 1.01–1.87), p = 0.041]." (PMID 26612435, 2015). "Analysis in the subgroup of infertile men with semen abnormalities according to the WHO criteria (65.1% of infertile subjects) revealed a significant association of TGFB3 rs2284792 variant with infertility; differences were significant for overall comparison, dominant model and allele frequency." (PMID 26612435, 2015). "However, minor allele frequency (MAF) was higher among infertile subjects in case of all the studied SNPs, reaching statistical significance level for TGFB3 rs2284792 (p = 0.025)." (PMID 26612435, 2015). "Significant association for TGFB3 rs3917158 SNP could also be observed for that subgroup analysis (p < 0.05 for dominant model and increased frequency of heterozygotes among infertile men with semen abnormalities, p = 0.056 for differences in minor allele frequency)." (PMID 26612435, 2015). "Due to strong linkage between the TGFB3 SNPs, haplotype frequencies were assessed, in both infertile and control groups." (PMID 26612435, 2015). "When the studied TGFB3/TNF genotypes were analyzed for the presence of potential association with sperm parameters, no significant genotype-dependent differences were observed among infertile men." (PMID 26612435, 2015). "Therefore, altered status for TGF-β3 generation produced by polymorphic variants in TGFB3 gene may affect function and integrity of the blood-testis barrier, thus leading to infertility." (PMID 26612435, 2015). "However, separate analysis of sperm parameters in normozoospermic infertile men and infertile men with semen abnormalities revealed no significant genotype-related differences, but lower percentage of motile spermatozoa was observed in TGFB3 rs2268626 and rs2284792 minor homozygotes." (PMID 26612435, 2015).
lung carcinoma (6 papers, 2013 to 2022). "Next, to identify the specific source of TGF-β at the cellular level, we analyzed the expression of TGFB1, TGFB2, and TGFB3 using the sc-RNAseq datasets of 33K PBMC and 52K lung cancer cells." (PMID 35069521, 2021). "Alternatively, as in lung cancer, the role of Col 1 in EMT is indirect and can be mediated via TGFβ3 expression." (PMID 32411604, 2020). "Restoration of SIX3 in lung cancer cells lacking endogenous SIX3 suppressed cell proliferation and migration, and downregulated a number of genes involved in proliferation and metastasis such as S100P, TGFB3, GINS3 and BAG1." (PMID 23977152, 2013).
renal fibrosis (6 papers, 2021 to 2025). A final common manifestation of a wide variety of chronic kidney diseases characterized by glomerulosclerosis and tubulointerstitial fibrosis. "The independent role of TGFβ2 and TGFβ3 in XLAS associated renal fibrosis is therefore worthy of further investigation." (PMID 40075271, 2025). "Four-month-old Tgfb3+/− mice exhibited incipient renal fibrosis with epithelial–mesenchymal transition, in addition to glomerular basement membrane thickening and podocyte foot process effacement associated with albuminuria." (PMID 34431499, 2021). "Male Tgfb3+/− mice at 4 months of age exhibit renal fibrosis, EMT and glomerular damage with foot process effacement in podocytes, and show albuminuria, loss of renal function, lipid accumulation, lipid metabolism deregulation, insulin resistance and mitochondrial dysfunction with oxidative stress." (PMID 34431499, 2021). "Our study observed a concurrent upregulation of all three isoforms and interestingly a relatively higher upregulation of TGFβ2 than TGFβ1/TGFβ3 in both tissues and cells, possibly suggesting that TGFβ2 may critically contribute to XLAS associated renal fibrosis." (PMID 40075271, 2025). "This is an unexplored area that could shed light onto the link between TGFβ3 and renal fibrosis." (PMID 34431499, 2021).
asthma (5 papers, 2019 to 2023). "Expression of isoforms of TGFβ 1 - 3 cytokines is influenced by tagging single nucleotide polymorphisms (SNPs) in the TGFβ1, TGFβ2 and TGFβ3 genes, which may be associated with asthma and other diseases." (PMID 35774789, 2022). "Expression of isoforms 1–3 of TGFβ cytokine is influenced by tagging polymorphisms in the TGFβ1, TGFβ2 and TGFβ3 gene, and these SNPs may be associated with the risk of asthma development and severity as well as with other diseases." (PMID 34620181, 2021). "Our purpose was to determine whether genotypes of MAC/SNP TGFβ1, TGFβ2, and TGFβ3 are related to the level of asthma control, measured with the application of the Asthma Control Test (ACTTM) in asthmatics and healthy controls." (PMID 34620181, 2021). "Their functions and effects on the expression of TGFβ1, TGFβ2 and TGFβ3 mRNA, as well as a new pool not yet studied in asthma, had been known before." (PMID 35774789, 2022).
Hypertension (5 papers, 2015 to 2025). The presence of chronic increased pressure in the systemic arterial system. "Transforming growth factor-beta 3 (TGF-β3), plays an essential role in these processes, and is known to be involved in the pathogenesis of hypertensive disorders in pregnancy 36-39 and some forms of OFCs 36,40." (PMID 26848196, 2015).
pancreatic cancer (5 papers, 2002 to 2025). "GO enrichment of each ColX module revealed multiple genes implicated in ossification, such as RUNX2 and TGFB3, both of which have been shown to play a role in OA, influence developmental pathways such as Wnt signaling, and contribute to EMT in breast and pancreatic cancer." (PMID 39939916, 2025). "This 3-gene predictive biomarker (TGFB3, IGF2, and SMO) was found to correlate with tumor growth inhibition in preclinical patient-derived pancreatic cancer xenograft models." (PMID 31338636, 2020). "It is also possible that TGFB3’s role is more prominent in developmental or wound-healing contexts and does not independently drive aggressive tumor behavior in pancreatic cancer." (PMID 40650134, 2025).
rheumatoid arthritis (5 papers, 2012 to 2025). A chronic, systemic autoimmune disorder characterized by inflammation in the synovial membranes and articular surfaces. "We evaluated PDGFA, TGFB1, TGFB2, and TGFB3 role in the diagnosis of ILD associated with rheumatoid arthritis (RA), systemic sclerosis (SSc), and inflammatory myopathies (IM)." (PMID 41226758, 2025). "For HLBW and SBW, TGFB3 and TLR4 were enriched to the pathway of rheumatoid arthritis." (PMID 38200769, 2023).
Rienhoff syndrome (5 papers, 2016 to 2025). Loeys-Dietz syndrome-5 (LDS5), also known as Rienhoff (pronounced REENhoff) syndrome, is characterized by syndromic presentation of aortic aneurysms involving the thoracic and/or abdominal aorta, with risk of dissection and rupture. "The patient in case 14_63, her maternal uncle with AD, and her unaffected sister had a heterozygous variant in TGFB3, NM_003239.5:c.412T>G, classified as a VUS on ClinVar for Rienhoff syndrome (Loeys–Dietz syndrome 5) resulting in a p.Ser138Ala." (PMID 40194966, 2025). "LDS type 5 (Rienhoff syndrome) is caused by mutation in the TGFB3 gene that encodes a nonfunctional TGF-β3 ligand." (PMID 36292765, 2022).
systemic sclerosis (5 papers, 2019 to 2025). A chronic disorder, possibly autoimmune, marked by excessive production of collagen which results in hardening and thickening of body tissues. "A previous report has additionally found an association between TGFβ2, TGFβ3, and TIMP1 in systemic sclerosis, which may ultimately be due to the contribution of IGF-II, based on the results of this study." (PMID 31765403, 2019). "In patients suffering from systemic sclerosis, the anti-TGFB monoclonal antibody fresolimumab, which targets the 3 TGFB isoforms (TGFB1, TGFB2, and TGFB3), was shown to be well tolerated and clinically efficient in a phase II clinical trial." (PMID 31779094, 2019).
thoracic aortic aneurysm (5 papers, 2016 to 2024). An aneurysm formed in the wall of the proximal portion of the descending aorta proceeding from the arch of the aorta. "Indeed, pathogenic variants or deficiency of TGF-β pathway genes, including TGFB2, TGFB3, TGFBR1, TGFBR2, and SMAD3, confer risks for aortic destruction and thoracic aortic aneurysm formation." (PMID 38916960, 2024).
aneurysm (4 papers, 2015 to 2025). Bulging or ballooning in an area of an artery secondary to arterial wall weakening. "In summary, our study highlights that TGFB1 expressed by PBMCs primarily contributes to aneurysm formation, while TGFB3 is associated with aneurysm rupture." (PMID 40563991, 2025). "Moreover, TGFB3 expression demonstrated diagnostic relevance in identifying ruptured aneurysms, with an AUC of 0.792." (PMID 40563991, 2025). "Evaluating gene expression in PBMCs provides novel insights into the involvement of inflammatory cells and TGFB1 and TGFB3 in aneurysm formation and rupture." (PMID 40563991, 2025). "Additionally, we plotted the ROC curve for TGFB1 expression, demonstrating its utility in identifying aneurysms (AUC = 0.671), whereas TGFB3 expression was significantly effective in identifying ruptured aneurysms (AUC = 0.792)." (PMID 40563991, 2025). "Moreover, TGFB3 expression was significantly higher in PBMCs of patients with RIA compared to healthy controls, suggesting a potential role for TGFB3 in aneurysm rupture." (PMID 40563991, 2025). "The low penetrance of TAA(D) and/or non-aortic arterial involvement in both our TGFB3 p.(Asp263His) founder cohort and literature suggests the need for additional genetic or environmental modifiers to provoke the aneurysm phenotype." (PMID 37719708, 2023).
breast tumors (4 papers, 2014 to 2023). "Significantly higher TGFB1 and TGFB3 mRNA levels and lower TGFBR2 mRNA levels were observed in the primary breast tumours compared with their matched normal tissues." (PMID 26703884, 2015). "In breast tumors from both Asian and Black groups, TGFB3 showed a significant negative correlation with most of the microbial biomarkers including Xanthomonas, Amycolatopsis, Pseudomonas and Succinomonas." (PMID 36702853, 2023).
cataract (4 papers, 2011 to 2022). Partial or complete opacity of the crystalline lens of one or both eyes that decreases visual acuity and eventually results in blindness. "Our results revealed that TGFβ1 was a predominant isoform in ALCs, whereas TGFβ3 was a major isoform in PBMCs in patients with congenital and traumatic cataracts." (PMID 22128246, 2011). "In the present study, real-time quantitative reverse transcription (QRT)-PCR was applied to investigate the changes in TGFβ1, TGFβ2, and TGFβ3 gene expression in fragments of ALCs and PBMCs from pediatric patients with congenital and traumatic cataracts." (PMID 22128246, 2011). "For traumatic cataracts, a positive correlation was only observed between the expression of TGFβ1 and TGFβ2 in ALCs, whereas for PBMCs, a positive correlation was only affirmed between the expression of TGFβ1 and TGFβ3." (PMID 22128246, 2011). "Compared with the cataract group, the concentration of IL-8, MMP-2, MMP-3, MMP-9, TGFβ-1, TGFβ-3, and TNF-α was significantly increased in subjects with JIAUwG or JIAUwoG." (PMID 29675026, 2018). "TGFβ1, TGFβ2, and TGFβ3 isoforms were detected in ALC and PBMC samples obtained from patients with congenital and traumatic cataracts." (PMID 22128246, 2011). "In ALCs, there was no significantly different expressions of TGFβ1, TGFβ2, and TGFβ3 between congenital and traumatic cataracts (TGFβ1 p=0.78, TGFβ2 p=0.75, TGFβ3 p=0.23, Mann–Whitney U test)." (PMID 22128246, 2011).
cleft lip (4 papers, 2012 to 2025). Congenital defect in the upper lip where the maxillary prominence fails to merge with the merged medial nasal prominences. "Transforming Growth Factor-Beta 3 (TGF-β3) is one of the strongest candidate gene for cleft lip and palate in humans." (PMID 22143699, 2012). "Previous studies have proposed Transforming growth factor - beta 3 (TGF-β3) gene as a key player in contributing to non-syndromic cleft lip and palate, however none of the studies have yet included Indian population." (PMID 22143699, 2012).
colon carcinoma (4 papers, 2014 to 2023). "However, in CT26 colon cancer, there is a relatively greater expression of TGFβ1 than TGFβ3 by comparison of MFI values." (PMID 34789823, 2021).
COVID-19 (4 papers, 2021 to 2024). A disease caused by infection with severe acute respiratory syndrome coronavirus 2. "Another key criterion in distinguishing patients from other infections is the methylation level of TGFB3 (cg06958766), which is hypomethylated in COVID-19 patients (especially ICU and death patients)." (PMID 36212830, 2022). "Existing studies have demonstrated that TGFB3 is a gene related to immune dysregulation in cardiovascular disease, and its expression is also dysregulated in COVID-19." (PMID 36212830, 2022). "In addition, TGFβ1, TGFβ3, IL-10, and IL-6 were prognostic makers for the early phase of COVID-19 severity, consistent with previous reports." (PMID 37569646, 2023). "In addition, TGFβ1, TGFβ3, IL-6, and IL-10 may be influential biomarkers of COVID-19 severity during the early phase of infection, whereas Th2 cytokines, IL-4 and IL-13, may be markers of persisting severity." (PMID 37569646, 2023). "The association of the methylation level of TGFB3 with the clinical outcome of COVID-19 infection has not been revealed, and such level is speculated to be possibly associated with poor clinical response to COVID-19." (PMID 36212830, 2022). "This was observed for TGFB3, CCL4, IL15, and IL20RA in both ICM samples vs. COVID-19 samples and NIDCM samples vs. COVID-19 samples." (PMID 34071557, 2021).
endometrial carcinoma (4 papers, 2009 to 2014). A malignant tumor arising from the epithelium that lines the cavity of the uterine body. "Further, BPA up-regulates the expression of other TGFβ isoforms, TGFβ2 and TGFβ3 transcripts but not TGFβ1, in neural tissue and endometrial cancer cells, respectively." (PMID 24586524, 2014).
osteoporosis (4 papers, 2017 to 2021). A condition of reduced bone mass, with decreased cortical thickness and a decrease in the number and size of the trabeculae of cancellous bone (but normal chemical composition), resulting in increased fracture incidence. "The expression of TGFB3 was detected in osteoblasts of patients with osteoporosis." (PMID 32496000, 2020). "Our findings suggested that SOX6, ACE, SYK and TGFB3 may play important roles in the bone formation of osteoporosis in postmenopausal women." (PMID 32496000, 2020).
osteosarcoma (4 papers, 2003 to 2023). A usually aggressive malignant bone-forming mesenchymal neoplasm, predominantly affecting adolescents and young adults. "However, TGFB3 expression has been correlated with a poor prognosis in osteosarcoma." (PMID 36980562, 2023). "Meanwhile, some hub genes have been reported involved in the tumorigenesis and progression of osteosarcoma, such as ITGAV, POSTN, COL1A1, TGFB1, TGFB3, and ITGAV." (PMID 32582282, 2020).